APLN (apelin)
Description:
Peptide hormone that functions as endogenous ligand for the G protein-coupled apelin receptor (APLNR/APJ), that plays a role in cadiovascular homeostasis. Functions as a balanced agonist activating both G(i) protein pathway and beta-arrestin pathway of APLNR. Downstream G proteins activation, apelin can inhibit cAMP production and activate key intracellular effectors such as ERKs. On the other hand, APLNR activation induces beta-arrestin recruitment to the membrane leading to desensitization and internalization of the receptor. Apelin blunts cardiac hypertrophic induction from APLNR on response to pathological stimuli, but also induces myocardial hypertrophy under normal conditions. Apelin-36 dissociates more hardly than (pyroglu)apelin-13 from APLNR (By similarity). Involved in the regulation of cardiac precursor cell movements during gastrulation and heart morphogenesis (By similarity). Has an inhibitory effect on cytokine production in response to T-cell receptor/CD3 cross-linking; the oral intake of apelin in the colostrum and the milk might therefore modulate immune responses in neonates (By similarity). Plays a role in early coronary blood vessels formation (By similarity). Mediates myocardial contractility in an ERK1/2-dependent manner (By similarity). May also have a role in the central control of body fluid homeostasis by influencing vasopressin release and drinking behavior (By similarity). (Microbial infection) Endogenous ligand for the apelin receptor (APLNR), an alternative coreceptor with CD4 for HIV-1 infection. Inhibits HIV-1 entry in cells coexpressing CD4 and APLNR. Apelin-36 has a greater inhibitory activity on HIV infection than other synthetic apelin derivatives.
Synonyms: APEL; XNPEP2
Tractability: Antibody: UniProt places it where antibodies can reach, with high confidence; its Gene Ontology location is reachable by antibodies, with high confidence; UniProt predicts a signal peptide or a membrane-spanning region.
Chemical probes: apelin-17
Gene: Protein-coding gene on chromosome X (129,645,259 to 129,654,959, reverse strand). Ensembl gene ENSG00000171388.
Subcellular location: Secreted; Secreted, extracellular space
Pathways (Reactome):
Signal Transduction: G alpha (i) signalling events; Peptide ligand-binding receptors
Gene Ontology:
Molecular function: apelin receptor binding; hormone activity; signaling receptor binding
Biological process: apelin receptor signaling pathway; negative regulation of fibroblast growth factor receptor signaling pathway; negative regulation of gene expression; negative regulation of vascular associated smooth muscle cell proliferation; positive regulation of G protein-coupled receptor internalization; positive regulation of miRNA transcription; positive regulation of vascular endothelial cell proliferation; coronary vasculature development; drinking behavior; immune response; lactation; negative regulation of blood pressure; positive regulation of heart contraction; signal transduction
Cellular component: extracellular region
Homologues: Orthologues: rabbit APLN (86% identical), dog APLN (84% identical), mouse Apln (83% identical), pig APLN (83% identical), guinea pig APLN (82% identical), rat Apln (82% identical), tropical clawed frog apln (55% identical), zebrafish apln (35% identical).
Diseases named in the same sentence as APLN in open-access papers:
APLN is named in the same sentence as 369 diseases in open-access papers, as found by Europe PMC text mining. Sharing a sentence is not in itself a finding about the gene and the disease. The quoted sentences say what the papers report.
Obesity (163 papers, 2011 to 2026). Accumulation of substantial excess body fat. "Circulating APLN levels are higher in people with obesity and T2D and inversely associated with insulin sensitivity, suggesting either APLN resistance or increased secretion from adipose tissue." (PMID 40171198, 2025). "In retrospective exploratory research, increased tumor apelin expression and obesity were independently linked to lower pathological complete response rates in 62 early BCa patients treated with taxane and anthracycline-based neoadjuvant chemotherapy." (PMID 39040042, 2024). "Fluctuations in the plasma levels of APLN are observed with weight variations, associating it directly with obesity." (PMID 39109340, 2024). "There are several limitations in our study including the cross-sectional design, which precludes us from identifying the causal direction between serum apelin-12 and obesity-related clinical and biochemical markers and MetS components in children with DS." (PMID 37930396, 2024). "APLN encodes a peptide hormone secreted by adipocytes, involved in the regulation of various metabolic functions and upregulated by insulin and obesity." (PMID 36978128, 2023). "Various recent studies associated the serum Apelin level with fluctuation in body weight and obesity." (PMID 37706122, 2023). "Pregnant women with obesity exhibited increased apelin levels which causes a decrease in frequency and strength of myometrial contractions." (PMID 37424869, 2023). "The association of apelin and lower uterine contractility in pregnant women with obesity deserves further evaluation." (PMID 37175743, 2023). "The apelin–APJ system can be considered a potential therapeutic target in the management of obesity-associated metabolic dysfunction and reproductive disorders." (PMID 37424869, 2023). "In clinical and experimental studies, serum apelin levels are increased in obesity and insulin-resistant status, whereas apelin deficiency increases adiposity and blood fatty acid levels, and apelin overexpression is resistant to obesity." (PMID 37670786, 2023). "Serum apelin level is increased in obesity and insulin-resistant status, whereas apelin deficiency increases adiposity and blood fatty acid levels, and apelin overexpression is resistant to obesity." (PMID 37670786, 2023). "Previous studies have reported that apelin (a peptide hormone linked with obesity and diabetes) and its receptor inhibit vascular injury in diabetes, including the endocrine response to stress, lipid metabolism, homeostasis and angiogenesis." (PMID 36902363, 2023). "Apelin is a newly-described adipokine produced and secreted by adipocytes that increases under conditions of obesity, mainly associated with hyperinsulinemia." (PMID 36291097, 2022). "In fact, insulin stimulates apelin synthesis and release in adipocytes, and plasma apelin level markedly increases in obesity associated with insulin resistance and hyperinsulinemia." (PMID 35610700, 2022). "In contrast, higher circulating levels indicate apelin resistance and are associated with obesity and IR." (PMID 35008925, 2022). "Few studies indicated positive associations between apelin and obesity-related cancers such as endometrial and breast cancer." (PMID 36230579, 2022). "Apelin is a new adipokine that is secreted by adipocytes, and is associated with insulin resistance (IR), inflammation, and obesity." (PMID 35610700, 2022). "Among the multiple dysregulations associated with obesity, increased level of the apelin adipokine has been recently shown to be directly involved in the association between obesity and increased breast cancer progression." (PMID 33972642, 2021). "In conclusion, in this retrospective exploratory study on 62 early BC patients treated with taxane and anthracycline-based NAC, obesity and high tumor apelin expression were independently associated with poorer pCR rates." (PMID 33972642, 2021).
Obesity (continued). "In the multivariate logistic regression, obesity and high tumoral apelin expression were associated with a reduced response to NAC in our cohort." (PMID 33972642, 2021). "In this study, we deliberately dissociated increased apelin levels caused by obesity from additional disorders associated with obesity and found that the increased TNBC growth is slightly smaller than the effect observed in obese mice." (PMID 32681609, 2020). "There is a relationship between obesity and the plasma levels of apelin; apelin upregulation and an increase in its plasma levels were reported in obesity in association with hyperinsulinemia." (PMID 33278072, 2020). "Visfatin, chemerin, and apelin have been shown to be associated with obesity and glucose metabolism, their potentials to be used as novel biomarkers are somewhat inconclusive based on current evidence." (PMID 32561824, 2020). "Apelin is a new hormone that has been identified recently and its role in molecular changes is associated with type 2 diabetes, obesity, and cardiovascular disorders." (PMID 33278072, 2020). "Among females, the APLN T-1860C polymorphism (OR = 4.39, 95% CI = 1.25–15.28) and apelin concentration (OR = 0.45, 95% CI = 0.23–0.92) were significantly associated with obesity (P < 0.05)." (PMID 32998691, 2020). "The APLN T-1860C polymorphism (OR = 4.39, 95% CI = 1.25–15.28) and apelin concentration (OR = 0.45, 95% CI = 0.23–0.92) were significantly associated with obesity among female children (p < 0.05) only, after adjusting for potential covariates." (PMID 32998691, 2020). "To further investigate the potential implication of apelin in the association between obesity and TNBC growth, we reproduced the increase of apelin observed during obesity by chronically administering apelin using osmotic mini pumps." (PMID 32681609, 2020). "Although the pathogenesis of obesity is complex and not well understood, our investigation proposes that the APLN T-1860C polymorphism exerted a sex-specific effect on obesity in Thai children." (PMID 32998691, 2020). "The increase of apelin levels in type 2 diabetes mellitus (T2DM) or obesity indicates an association between apelinemia and impaired glucose regulation." (PMID 32087711, 2020). "Existing evidence—especially in children—concerning apelin and its relation to obesity and cardiometabolic risk factors remain less clear, with published results being inconsistent." (PMID 32998691, 2020). "Taken together, measurement of apelin level will provide valuable information to elucidate the underlying mechanism between obesity and diastolic dysfunction as well as to explore therapeutic strategies for diastolic dysfunction." (PMID 30872595, 2019). "Previous studies have demonstrated that dysregulation of apelin signaling was associated with pathological states, such as T2D and obesity." (PMID 30868058, 2019). "They found that apelin was reduced in youngsters with obesity but that the A allele was associated with higher apelin levels in this instance." (PMID 31492821, 2019). "Future studies is needed to evaluate the association between serum apelin levels and diastolic function to elucidate the underlying mechanism regarding obesity-related diastolic dysfunction." (PMID 30872595, 2019). "Previous reports also imply that higher apelin levels are associated with both insulin resistance and chronic inflammation in individuals with obesity." (PMID 31827626, 2019). "In recent years, interest has grown about some novel adipokines, chemerin, visfatin, resistin and apelin, which have been found to be strongly associated with obesity and insulin-resistance." (PMID 31505789, 2019). "The metabolic effects of apelin described in different mouse models (diet-induced obesity, transgenic models) have underlined the beneficial roles of apelin on both energy metabolism and insulin sensitivity." (PMID 25914650, 2015).
Obesity (continued). "Further prospective studies with large samples are needed to clarify the role and mechanisms of apelin in association with obesity-related markers in a sub-population of obese children." (PMID 24475149, 2014). "Apelin also reduces MS risk and, in obesity, increased adipose and systemic levels of apelin have been detected." (PMID 25548896, 2014). "Insulin resistance is common to both obesity and type 2 diabetes, and apelin is linked with obesity-associated variations of insulin sensitivity status." (PMID 24475149, 2014). "Expression of apelin in adipocytes is shown to be increased in mouse models of obesity associated with hyperinsulinemia, and apelin levels paralleled plasma insulin levels during fasting and refeeding of mice." (PMID 24475149, 2014). "Apelin inhibits insulin secretion in mice, which suggests a link between apelin and glucose homeostasis, and over-production of apelin in the obese is associated with obesity-related disorders such as type 2 diabetes." (PMID 23874984, 2013). "Insulin increases apelin synthesis in adipocytes and plasma apelin level rises in obesity associated with insulin resistance." (PMID 23691290, 2013). "It is interesting to note that the relationship between apelin and insulin or TNFα during obesity and obesity-associated disorders was still maintained at the end of the aerobic exercise but was dependent on the magnitude of insulin sensitivity." (PMID 23653851, 2012). "Apelin regulates body fluid homeostasis and cardiovascular functions through the apelin receptor, APJ, and the level of plasma apelin markedly increases in obesity that is associated with insulin resistance and hyperinsulinemia." (PMID 21437254, 2011). "In another investigation, it was also noted that apelin mRNA expression was increased in subcutaneous adipose tissue as well as in TNBC in mice, and that increased apelin expression associated with increased levels of obesity in mice led to increased growth and brain metastasis of TNBC." (PMID 40414892, 2025). "Apelin has also been linked to the development of TNBC in the context of obesity." (PMID 40414892, 2025). "Increased plasma APLN concentrations have been associated with obesity and type 2 diabetes." (PMID 39109340, 2024). "Simultaneously, increased levels of apelin, chemerin, and lipocalin-2 suggest complex metabolic disorders that may be associated with obesity and IR." (PMID 39201400, 2024). "Venn diagram analysis revealed that seven DEGs (CXCL8, MLXIPL, CREB3L1, EGR1, NOTCH3, ACTA2, and SERPINE1) were associated with both obesity and diabetes-associated pathways, including non-alcoholic fatty liver disease, insulin resistance, thermogenesis, and apelin signaling pathways." (PMID 38570815, 2024). "Since leptin and adiponectin modulate steroidogenesis, gonadotrophins release, and fertility, apelin replacement may improve reproductive dysfunction associated with obesity or T2DM through increasing adiponectin and the adiponectin/leptin ratio." (PMID 37424869, 2023). "Additionally, apelin is referred to as a member of adipokines that has been implicated in diabetes and obesity." (PMID 37344635, 2023). "Moreover, in experimental obesity models that are associated with hyperinsulinemia, apelin levels significantly increased." (PMID 37424869, 2023). "Additionally, associations between circulating apelin and obesity suggest potential effects on chemotherapy response and obesity-related cancers." (PMID 36230579, 2022). "However, apelin levels were already decreased in patients with underlying risk factors, including hypertension and obesity, and remained low after infection with SARS-CoV-2." (PMID 36352477, 2022). "Apelin-13 is a small peptide found in the adipose tissue that is thought to be implicated on energy metabolism and insulin sensitivity, being also associated with obesity." (PMID 35187089, 2022). "The increased levels of apelin are observed in obesity-associated hyperinsulinemia." (PMID 34212049, 2021).
Obesity (continued). "In addition, there is a growing appreciation of the importance of newer adipokines, such as resistin, visfatin, and apelin, in obesity-linked cancers." (PMID 33535537, 2021). "Another lesser known adipokine, apelin, appeared to be linked to obesity and glucose homeostasis." (PMID 32561824, 2020). "Therefore, the genetic polymorphism of APLN T-1860C and apelin concentration appeared to affect the susceptibility to obesity." (PMID 32998691, 2020). "The purposes of this study were to examine apelin concentrations and anthropometric-cardiometabolic parameters in obese and non-obese children and to identify associations of APLN T-1860C and APLNR G212A polymorphisms with apelin levels and obesity among Thai children." (PMID 32998691, 2020). "However, relatively few studies have observed a correlation between APLNR G212A polymorphism with circulating apelin level and obesity phenotypes." (PMID 32998691, 2020). "Therefore, our study was interested in examining links of the APLNR G212A polymorphism with apelin concentration and obesity phenotypes among Thai children." (PMID 32998691, 2020). "More recently, apelin is also proposed as an adipokine mediator which might have an adaptive response to prevent chronic inflammation associated with obesity." (PMID 31827626, 2019). "Another study reported increased apelin-12 serum concentration in patients with obesity and obesity-related insulin resistance, which could be caused by impaired insulin sensitivity." (PMID 29875677, 2018). "Although serum apelin levels are increased in obesity associated with insulin resistance and hyperinsulinemia, its regulatory role on OS in adipocytes remains unknown." (PMID 25548896, 2014). "Linear regression analysis of associations of apelin-12 levels with obesity-related markers." (PMID 24475149, 2014). "In addition, vitamin C supplementation reduces the gene expression of apelin, an adipokine associated with insulin resistance, obesity and increased inflammation in animal models." (PMID 22703731, 2012). "On the other hand, studies also demonstrated that apelin expression was higher in animal models of obesity associated with hyperinsulinemia, in addition to its role in adipogenesis and steatosis; all of which contribute largely to fibrosis progression, as well as higher degree of inflammation." (PMID 22007137, 2011). "However, it remains uncertain whether high apelin expression in tumours is directly associated with obesity." (PMID 40414892, 2025). "Thus, the reduction of apelin levels after weight loss should further be evaluated with insülin sensitivity indices, and it is crucial to comprehend how this adipokine contributes to problems linked to obesity." (PMID 41417360, 2025). "While obesity may upregulate apelin levels, this occurs only when the condition is associated with hyperinsulinemia; thus, what mainly produces this augmentation in apelin expression appears to be increased insulin." (PMID 39457235, 2024). "However, we hypothesised that apelin concentrations may be associated with obesity and cardiometabolic risk factors in Thai children." (PMID 32998691, 2020). "Therefore, the APLN T-1860C polymorphism should be studied prospectively in a wider population to fully understand the mechanism underlying the relationship of this gene polymorphism in the etiopathology of obesity, especially in children." (PMID 32998691, 2020). "Furthermore, the APLN T-1860C polymorphism may influence susceptibility to obesity among female children." (PMID 32998691, 2020). "Thus, it is plausible that the genetic variant of APLN associated with the susceptibility of obesity may influence the apelin and its receptor system, which controls feeding behaviour." (PMID 32998691, 2020).